IL24 (interleukin 24)
Description:
Multifunctional cytokine mainly produced by T-cells that plays a regulatory role in immune response, tissue homeostasis, host defense, and oncogenesis. Possesses antiviral functions and induces the type I interferon response during influenza infection. Signals through two receptor complexes IL20RA/IL20RB or IL20RB/IL22RA1. In turn, stimulates the JAK1-STAT3 and MAPK pathways and promotes the secretion of pro-inflammatory mediators including IL8 and MMP1. Intracellularly, maintains endoplasmic reticulum homeostasis by restricting the eIF2alpha-CHOP pathway-mediated stress signal (By similarity). In addition, acts as a quality control mechanism for the ubiquitin proteasome system by alerting the cell to proteasome dysfunction through activation of PKR/EIF2AK2 (By similarity).
Synonyms: IL-24; MDA-7; MDA7; ST16; IL10B; Mob-5; C49A; FISP; MOB5
Tractability: Antibody: UniProt places it where antibodies can reach, with high confidence; its Gene Ontology location is reachable by antibodies, with high confidence; UniProt predicts a signal peptide or a membrane-spanning region. PROTAC: UniProt records ubiquitination sites on it.
Gene: Protein-coding gene on chromosome 1 (206,897,443 to 206,904,139, forward strand). Ensembl gene ENSG00000162892.
Subcellular location: Secreted
Pathways (Reactome):
Immune System: Interleukin-20 family signaling
Gene Ontology:
Molecular function: protein binding; cytokine activity
Biological process: apoptotic process; cellular response to interleukin-4; immune response; regulation of cell population proliferation; cellular response to lipopolysaccharide; negative regulation of cell migration; negative regulation of cell population proliferation; positive regulation of cell population proliferation; signal transduction
Cellular component: extracellular region; receptor complex
Genetic constraint (gnomAD): Loss-of-function variants: 24 observed, 27.32 expected, observed/expected ratio (o/e) 0.88, 90% interval 0.63 to 1.24. The upper end of that interval is the gene's LOEUF score, 1.24, which puts it in group 5 of 6, group 1 being the genes least tolerant of losing a copy. Missense variants: 235 observed, 244.26 expected, observed/expected ratio (o/e) 0.96, 90% interval 0.86 to 1.07. Synonymous variants: 95 observed, 96.8 expected, observed/expected ratio (o/e) 0.98, 90% interval 0.83 to 1.16.
Homologues: Orthologues: chimpanzee IL24 (99% identical), macaque IL24 (93% identical), guinea pig IL24 (60% identical), pig IL24 (60% identical), dog IL24 (59% identical), mouse Il24 (59% identical), rat Il24 (57% identical), zebrafish il22 (16% identical). Paralogues in human: IL20 (26% identical), IL19 (24% identical), IL10 (18% identical), IL26 (17% identical).
Diseases named in the same sentence as IL24 in open-access papers:
IL24 is named in the same sentence as 171 diseases in open-access papers, as found by Europe PMC text mining. Sharing a sentence is not in itself a finding about the gene and the disease. The quoted sentences say what the papers report.
melanoma (96 papers, 2006 to 2025). A malignant, usually aggressive tumor composed of atypical, neoplastic melanocytes. "Research has shown that structurally varied NSAIDs can trigger apoptosis in ovarian, prostate, renal, breast, and stomach cancer cell lines by activating melanoma differentiation-associated gene-7/Interleukin-24 (mda-7/IL-24)." (PMID 41018072, 2025). "IL-24, a cytokine from the IL-10 family with tumor-suppressive properties, was initially identified in studies on melanoma differentiation-associated gene-7 (MDA-7)." (PMID 40866941, 2025). "IL-24, initially identified as melanoma differentiation-associated gene-7 or MDA-7, is an anticancer cytokine within the IL-10 gene family." (PMID 39782693, 2025). "Taken together, these findings highlight a strong association between high IL-24 expression and enhanced antitumor immune responses in melanoma." (PMID 40866941, 2025). "IL‐24, originally referred to as melanoma differentiation associated protein‐7 (mda‐7), was discovered from the human HO‐1 melanoma cell line following treatment with recombinant interferon‐beta (IFN‐β) and mezerin, a protein kinase C (PKC) activator." (PMID 40338095, 2025). "Melanoma differentiation-associated gene 7 (Mda-7) encodes IL-24, which can induce apoptosis in cancer cells." (PMID 37280571, 2023). "IL-24 was discovered by subtractive hybridization from growth-arrested and terminally differentiated human melanoma cells, and was known as melanoma-differentiation-associated gene 7 (MAD-7)." (PMID 35054813, 2022). "Melanoma differentiation-associated gene-7/Interleukin-24 (mda-7/IL-24) is an exceptional therapeutic cytokine member of the IL-10 gene family, with immune-modulating activity." (PMID 33670594, 2021). "Melanoma differentiation associated gene-7/Interleukin-24 (MDA-7/IL-24) is a unique cytokine belonging to the IL-10 gene family that was cloned using subtraction hybridization in the early-nineties." (PMID 35008495, 2021). "The mechanism underlying a gradual decrease in expression during melanoma progression involves AU rich 3′ UTR elements (ARE) in the MDA-7/IL-24 transcript, which renders the MDA-7/IL-24 mRNA very unstable." (PMID 35008495, 2021). "Melanoma differentiation associated gene-7 (mda-7/IL-24) is a member of the IL-10 family of cytokines, with ubiquitous direct and “bystander” tumor-selective killing properties." (PMID 31489119, 2019). "In 2019, one novel study showed that melanoma differentiation-associated gene-7/interleukin-24 (mda-7/IL-24), a multifunctional cytokine, displayed broad-spectrum anticancer activity by regulating the function of DICER." (PMID 31572683, 2019). "Because IL-24, which was initially named melanoma differentiation-associated gene-7, suppresses the growth and induces apoptosis of cancer cells, the expression of IL-24 in colorectal cancer patients has been determined." (PMID 29967613, 2018). "Melanoma differentiation associated gene-7/interleukin-24 (mda-7/IL-24) has been initially identified by subtraction hybridization with a differentiation therapy model of human melanoma cells." (PMID 27203744, 2016). "Melanoma differentiation associated gene 7 (MDA-7)/IL-24, a secreted protein of the IL-10 family, functions as a cytokine at normal physiological levels expressed in tissues of the immune system, has shown a great potential as an anti-cancer gene." (PMID 27349517, 2016). "Melanoma differentiation associated gene-7(mda-7)/IL-24 is a unique member of the IL-10 gene family that stimulates antitumor immune response to promote cancer-targeted toxicity." (PMID 26788909, 2016). "The human melanoma differentiation-associated gene (mda)-7/IL-24 is a unique cytokine/tumor suppressor gene that belongs to the IL-10 cytokine family." (PMID 27602961, 2016). "In this study, melanoma differentiation associated gene-7/interleukin-24 (mda-7/IL-24) was chosen as the target therapeutic protein carried by the adenoviral vectors." (PMID 27322080, 2016).
melanoma (continued). "Melanoma differentiation associated gene-7 (mda-7), also known as Interleukin-24 (IL-24), encodes a secreted protein of the IL-10 gene family and is located on chromosome 1q32-33 in humans." (PMID 26474456, 2015). "Melanoma differentiation associated gene-7/interleukin-24 (mda-7/IL-24) encodes a tumor suppressor gene implicated in the growth of various tumor types including breast cancer." (PMID 26460950, 2015). "IL24 was originally implicated in terminal differentiation of human melanoma cells and subsequently shown to selectively kill cancer cells, inhibit tumor growth and invasion and metastasis in vitro and in vivo." (PMID 26304929, 2015). "Melanoma differentiation-associated gene 7 (MDA-7)/interleukin-24 (IL-24) protein is expressed in cells of the immune system and normal human melanocytes." (PMID 22588557, 2012). "TLS-CHOP knockdown inhibited growth of MLS cells, and induced an anticancer cytokine, melanoma differentiation-associated gene 7 (MDA-7)/interleukin-24 (IL-24) expression." (PMID 22588557, 2012). "The melanoma differentiation associated gene-7 (MDA-7), now known as Interleukin-24(IL-24), can inhibit the growth and induce the apoptosis of melanoma, along withovarian, lung, pancreas, prostate,and colon cancers." (PMID 22569271, 2012). "Melanoma differentiation associated gene-7/interleukin-24 (MDA-7/IL-24) is a naturally occurring anti-cancer cytokine that induces a strong tumor suppressive effect in various cancer cell types while sparing normal cells." (PMID 22808125, 2012). "MDA-7 (melanoma differentiation associated gene-7), also known as IL-24, was initially identified from cancer cells and found to be up-regulated in melanoma cells." (PMID 21524313, 2011). "In the present study, we have investigated an unexpected link between TGase-4 and the melanoma differentiation-associated gene-7/interleukin-24 (MDA-7/IL-24), a cytokine known to regulate the growth and apoptosis of certain cancer and immune cells." (PMID 21524313, 2011). "We have previously established that the pro-apoptotic cytokine melanoma differentiation associated gene-7/Interleukin-24 (mda-7/IL-24) is a crucial mediator of NSAID-induced apoptosis in prostate, breast, renal and stomach cancer cells." (PMID 21931671, 2011). "Up-regulating the expression of melanoma differentiation-associated gene-7/interleukin-24 (MDA-7/IL-24) can enhance the expression of Fas activated by cisplatin." (PMID 20470393, 2010). "Previous studies showed that the human melanoma differentiation-associated gene-7 (mda-7), also known as interleukin-24 (IL-24), has potent antitumor activity against human and murine cancer cells." (PMID 17274815, 2007). "Incited by the tentatively beneficial traits of this IL-10-family cytokine, we initially set out to investigate the signalling events underlying IL-24-induced direct as well as “bystander” killing of melanoma cells." (PMID 18074024, 2007). "Moreover, TGM4 overexpression in PC-3 prostate cancer cells reversed the adhesion, growth, and migration inhibitory effect of melanoma differentiation-associated gene-7/interleukin-24 (MDA-7/IL-24)." (PMID 40214422, 2025). "Melanoma differentiation associated gene-7/interleukin-24 (MDA-7/IL-24), a secreted protein of the IL-10 family, was first identified more than two decades ago as a novel gene differentially expressed in terminally differentiating human metastatic melanoma cells." (PMID 35008495, 2021). "We and others have extensively investigated and reported the underlying apoptotic mechanisms of IL-24 protein treatment and Ad.IL-24 infection in preclinical studies in several cancer cells, including melanoma, glioblastoma, breast, prostate, lung, colon, liver, and cervical cancer cells." (PMID 30424508, 2018). "Importantly, IL24 exposure induced apoptosis by reduction of pro-apoptotic Bcl2 proteins and caused a G2/M cell cycle arrest; a similar effect observed in melanoma cell lines treated with GSK126." (PMID 26304929, 2015).
melanoma (continued). "Melanoma differentiation associated gene-7/Interleukin-24 (MDA-7/IL-24) is a novel member of the IL-10 gene family that selectively induces apoptosis and toxic autophagy in a broad spectrum of human cancers, including breast cancer, without harming normal cells or tissues." (PMID 26474456, 2015). "Likewise, other agents such as Nelfinavir (an HIV protease inhibitor with anticancer activity) or Melanoma differentiation associated gene-7/interleukin 24 (mda-7/IL-24) activate an ER stress response that promotes autophagy and apoptosis of cancer cells." (PMID 20145727, 2010). "Both IL-2 and IL-24 are associated with melanoma tumour suppression in humans and it is now possible to study the role of these genes in the opossum model, as well as in the maintenance of transmissible allograft tumours in Tasmanian devil facial tumour disease." (PMID 17094811, 2006). "Intriguingly, introducing the IL-24 gene into melanoma cells resulted in a suppression of cell growth and colony formation, suggesting a potential therapeutic avenue." (PMID 40806452, 2025). "Together, these findings confirm that Vin promotes IL-24 secretion from melanoma cells, activating the IL-20R2 signaling axis to enhance CD8+ T cell cytotoxicity and amplifying antitumor immune responses." (PMID 40866941, 2025). "IL-24 was first identified by subtraction hybridization from terminally differentiating metastasis-derived human melanoma cells." (PMID 39744942, 2025). "It was reported that the tumour suppressor cytokine IL‐24 is downregulated during melanoma progression, and supplementing IL‐24 has been shown to reverse melanoma resistance to TMZ by downregulating MGMT." (PMID 39873425, 2025). "To further explore the role of IL-24 in this process, we collected conditioned medium (CM) from either Vin-treated or untreated melanoma cells and used it to treat Jurkat cells." (PMID 40866941, 2025). "Studies have revealed the presence of both IL‐24 mRNA and protein expression in normal melanocytes as well as early‐stage melanomas, which decline with disease progression, contributing to invasive and metastatic characteristics in melanoma." (PMID 40338095, 2025). "Specifically, early investigations revealed a notable decline in both gene and protein expression levels of IL-24 within the invasive regions of human melanomas." (PMID 40806452, 2025). "Further analysis indicated that IL-24 levels were significantly higher in melanoma patients who responded to anti-PD-1 therapy, although its expression did not vary substantially before and after treatment." (PMID 40866941, 2025). "Studies have shown that the expression of IL-24 is markedly diminished in advanced melanoma, with its levels being almost undetectable in metastatic cases, which aligns with its role as a tumor suppressor." (PMID 40866941, 2025). "These IL‐24 integrated MSCs (IL‐24‐iMSCs) were co‐cultured with B16‐F10 mouse melanoma cells and induced apoptosis." (PMID 40338095, 2025). "Adenovirus expressing M7S led to greater cellular apoptosis and tumor suppression compared with wild type IL‐24; enhanced anti‐tumor and bystander effects were observed in melanoma and prostate cancer xenograft models." (PMID 40338095, 2025). "To further explore the correlation between IL-24 expression in melanoma tumors, CD8+ T cell infiltration, the response to anti-PD-1 therapy, and its potential impact on patient prognosis, we first analyzed data from the public database." (PMID 40866941, 2025). "Despite being identified several decades ago as melanoma differentiation-associated gene-7 (MDA-7), IL-24 continues to reveal new aspects of its role in normal physiology and various human diseases, including cancer." (PMID 40806452, 2025). "Recent research has extended beyond melanoma, exploring IL-24 expression in various tumor types to assess its prognostic value." (PMID 40806452, 2025).
melanoma (continued). "Pharmacological (SB203580) and AdCMV‐Flag p38 (AGF)‐mediated p38 MAPK inhibition prevented the downregulation of Bcl2, thereby reversing IL‐24 mediated cellular apoptosis in melanoma cells." (PMID 40338095, 2025). "In another recent study, greater levels of IFN‐γ expressing CD8+ cells were identified in B16 melanoma syngeneic models in response to IL‐24." (PMID 40338095, 2025). "EPIC scoring of TCGA melanoma data revealed that the high IL-24 expression group showed a significant increase in B cell and CD8+ T cell infiltration compared to the low expression group." (PMID 40866941, 2025). "Introduction and exogenous expression of IL‐24 in human melanoma cell lines halted cell proliferation, demonstrating for the first time its potential antitumor activity." (PMID 40338095, 2025). "To validate the functional significance of the P38/MAPK/ATF3/IL-24 axis in vivo, we established melanoma xenograft models with stable knockdown of ATF3 or IL-24." (PMID 40866941, 2025). "Data from in vivo studies indicated that retro‐orbital injection of IL‐24‐iMSCs effectively inhibited the growth of melanoma tumors in subcutaneous mouse models." (PMID 40338095, 2025). "In this study, we demonstrated that vinburnine promotes IL-24 secretion from melanoma cells, leading to enhanced T-cell activity through IL-20R2." (PMID 40866941, 2025). "Studies also show that IL‐24 treatment triggers phosphorylation of eiF2α on the serine 51 residue in prostate cancer, melanoma, breast, and cervical cancer cells." (PMID 40338095, 2025). "The combined effects of PIKFYVE inhibitors and ectopic expression of IL24 protein were additive, thereby confirming the therapeutic potential of elevating IL24 levels in the treatment of melanoma." (PMID 38414326, 2024). "Inhibition of PIKFYVE activity in autophagy‐dependent melanoma cells and tumors upregulates IL24 expression with concomitant amplification of the PERK‐dependent ER‐stress response." (PMID 38414326, 2024). "Thapsigargin and tunicamycin each induced 3× the amount of IL24 RNA in melanoma A375 cells as did an equivalent concentration of WX8." (PMID 38414326, 2024). "Taken together, these results revealed that the PERK‐dependent ER‐stress response in melanoma cells triggered upregulation of IL24 gene expression." (PMID 38414326, 2024). "The average levels of IL24 RNA in patient derived melanomas are significantly greater than in samples of normal skin, suggesting that PIKFYVE inhibitors alone will have therapeutic potential against many autophagy‐dependent melanomas." (PMID 38414326, 2024). "Subsequent biochemical and genetic analyses revealed that PIKFYVE inhibitors induced a PERK‐dependent ER‐stress response that upregulated IL24 expression, which resulted in the termination of autophagy‐dependent melanoma cells in vivo as well as in vitro." (PMID 38414326, 2024). "PIKFYVE inhibitors selectively kill melanoma cells by disrupting lysosome homeostasis, which triggers an ER‐stress response that upregulates expression of glycosylated interleukin‐24 (IL24)." (PMID 38414326, 2024). "In recent years, some combined gene therapy approaches, such as the combination of jx-594 and ipilimumab for melanoma and IL-24 and GM-CSF for liver cancer, have also been gradually developed." (PMID 36817418, 2023). "In cancer cells, we were the first to show that IL-24 induces apoptosis independently of the JAK/STAT pathway in melanoma, breast, fibrosarcoma, and prostate cancer cell lines." (PMID 37444474, 2023). "IL-24 was detected in terminally differentiated human melanoma cells induced by interferon β and the protein kinase C activator mezerein." (PMID 38098005, 2023). "MDA-7/IL-24 is a member of the IL-10 family and has been strongly correlated to apoptosis induction in a variety of cancers including melanoma, breast, liver, prostate, ovarian, and nasopharyngeal cancer." (PMID 35814447, 2022).